IL6 (interleukin 6)
Diseases named in the same sentence as IL6 in open-access papers (continued):
Sharing a sentence is not in itself a finding about the gene and the disease.
tumor (continued). "The initial impact of cancer‐associated fibroblasts on tumour development depends primarily on the abnormal secretion of various proteins from exosomes, hepatocyte growth factor (HGF), tumour necrosis factor‐α (TNF‐α), interleukin 6 (IL‐6) and transforming growth factor‐β (TGF‐β) are included." (PMID 39950738, 2025). "Studies have shown that IL-6 could promote tumor proliferation, invasion and metastasis." (PMID 40264786, 2025). "Notably, α-HB subtype 2 exhibited significant enrichment in various immune and inflammatory pathways, including regulation of response to tumor cells, synaptic vesicle localization, and multiple interleukin-mediated signaling pathways (such as IL-6, IL-4, IL-2, and IL-15)." (PMID 41041634, 2025). "Furthermore, IL-6 is strictly related to immune responses affecting tumor progression." (PMID 40141175, 2025). "Researchers believe that this may be due to the close relationship between IL-6 and tumor immunity." (PMID 40433391, 2025). "Cytokines such as Il-6 and TGF-β induce differentiation to Th17, which is associated with chronic inflammatory conditions, whereas anti-inflammatory cytokines IL-10 and TGF-β induce Tregs differentiation, which suppresses immune responses and aids in tumor evasion." (PMID 40429961, 2025). "Furthermore, we investigated whether CD109 affects IL-6-induced tumorigenicity in SCC cells using an in vitro tumor spheroid formation assay." (PMID 40317079, 2025). "Furthermore, cytokines such as interleukin-6 (IL-6) and interleukin-23 (IL-23) help establish a tumor-promoting microenvironment by activating key transcription factors, including nuclear factor kappa B (NF-κB) and signal transducer and activator of transcription." (PMID 40572696, 2025). "In multiple cancers, tumor cores enriched with macrophages exhibit overlapping inflammatory and angiogenic signatures, further supporting the notion that inflammatory stimuli like IL-6 can drive macrophages toward a hybrid pro-inflammatory and pro-angiogenic state." (PMID 40429986, 2025). "Furthermore, tumor cells upregulate PLT production via the IL-6-TPO axis." (PMID 41357195, 2025). "Furthermore, adding exogenous IL-6 to tumor cell-derived CM also enhanced survival." (PMID 40718440, 2025). "Additionally, SCFA stimulate the production of key cytokines such as IL-6 and IL-12 and facilitate the activation of dendritic cells and neutrophils, thereby contributing to the establishment of an immunostimulatory tumor microenvironment and reinforcing anti-tumor immune mechanisms." (PMID 40944286, 2025). "Furthermore, FABP5 may contribute to inflammatory responses in tumor cells by modulating the expression of interleukin‐1 (IL‐1), IL‐6, and IL‐8, as well as parathyroid hormone‐related protein." (PMID 40178066, 2025). "Since tumor weight almost doubled between these two stages, the combined effects of increased expression and increased tumor size could explain the exponential rise in circulating levels of IL-6." (PMID 40124481, 2025). "Moreover, FOSL1 is involved in other important signaling pathways that affect tumor progression, such as the interleukin-6/signal transducer and activator of transcription 3 (IL-6/Stat3) pathway, the Wnt-β-catenin pathway, and other major carcinogenic pathways." (PMID 40821785, 2025). "This ratio may better reflect the immunosuppressive tumor microenvironment than absolute cytokine levels alone, as the anti-inflammatory effects of IL-10 may dominate when disproportionately elevated relative to IL-6." (PMID 40881684, 2025). "Additionally, the downregulation of oncogenes and cancer-associated genes, such as IL6, MMP2, and CCND2, may deprive the tumor cell of its growth advantage." (PMID 40043049, 2025). "Additionally, the same review proposed that constitutional symptoms, such as low-grade fevers and fatigue, may result from elevated levels of interleukin-6 produced by the tumor, which could complicate early diagnosis as well." (PMID 40896008, 2025).
tumor (continued). "Interestingly, IL6, known for its dual role as a pro-inflammatory cytokine and an anti-inflammatory myokine, exhibited a significant increase, suggesting a potential immune-modulatory effect of the decoction in the tumor microenvironment." (PMID 40746726, 2025). "The scalability of IL-6/OPN axis may also apply to IPFP in addition to tumor." (PMID 40664639, 2025). "Only the conditioned medium of TA-nanoARC produced an intense secretion of IL-6, a cytokine whose role in immunity is context-dependent, initially described as a pro-tumor agent, more recently found responsible for orchestrating the action of different anti-tumor effectors." (PMID 40943526, 2025). "IL-33 activates two pro-inflammatory factors, secreted IL-6 and IL-23, which lead to the expansion of Th17 cells and imbalance of Th17/Treg cells, ultimately leading to immune dysregulation, promoting the progression of inflammation and also promoting tumor growth in the tumor environment." (PMID 39925809, 2025). "Furthermore, the suppression of TNFα and IL6 suggests a diminished inflammatory response, which may impair T-cell effector function and cytokine-mediated anti-tumor immunity." (PMID 40407494, 2025). "Combined blockade of IL-6 or IL-10 or IL-17 may better improve the prognosis of tumor patients." (PMID 40040705, 2025). "Furthermore, co-culture experiments demonstrated that M2-polarised macrophages could effectively infiltrate tumour cells, promote tumour cell proliferation while inhibiting invasion, suggesting IL-6-mediated signalling in tumour progression." (PMID 40420192, 2025). "High IL-6 concentrations promote tumor progression after treatment and may decrease RT sensitivity." (PMID 39619013, 2024). "Furthermore, the inflammation-related interactions (Interleukin 6/Janus kinase/Signal Transducer and Activator of Transcription protein) signaling pathway is hyperactivated, turns out to perturbing anti-tumor immune responses to encourage tumor progression." (PMID 39273649, 2024). "However, some cytokines possess dual pro-tumor and anti-tumor properties, such as IL-6." (PMID 38294629, 2024). "Consequently, the reduction of tumor mass through systemic anti-tumor therapy could lead to diminished IL-6 production and subsequently to CRP normalization." (PMID 37695463, 2024). "Furthermore, NF-κB and STAT3 interact and cooperate in regulating the interaction of malignant cells and the tumor microenvironment, especially immune cells such as TAMs that release cell-stimulating growth factors and cytokines, including IL-6, IL-10, and TNF-α." (PMID 39061137, 2024). "IL-6 can increase the activity of HIF-1α in tumor cells via STAT3 signaling, and HIF-1α may activate GLUT-1 via the Phosphatidylinositol-3-kinase (PI3K) pathway, which shifts glucose metabolism from oxidative phosphorylation to anaerobic processes (the Warburg effect)." (PMID 39963655, 2024). "For example, TGF-β, FGF2, EGF, and interleukin 6 (IL-6) stimulate cancer cell proliferation; VEGF and platelet-derived growth factor (PDGF) promote angiogenesis; MMP-2 and MMP-9 degrade extracellular stroma; and CCL22 recruits Tregs lymphocytes to cause tumour immunosuppression." (PMID 39337393, 2024). "Furthermore, in addition, high levels of IL-6 may also impair the body’s anti-tumor immune surveillance function by inhibiting the activity of cytotoxic T cells, such as CD8+ T cells." (PMID 39727679, 2024). "This suggests that, even if IL-6 expression is the same in the whole tumor tissue, IL-6 may affect cancer cells differently, altering their proliferative, migratory, and invasive capacities due to differences in the distribution of IL6; however, further research is required to clarify the details." (PMID 39126553, 2024). "Notably, Ras-induced IL-6 secretion within the TME actively promotes tumor growth in vivo." (PMID 38799159, 2024).
tumor (continued). "Indeed, tumour cells secrete various cytokines, such as interleukin-6, which can increase the expression of the receptor activator of nuclear factor kappa-B ligand (RANKL) in osteoblasts, and activate osteoclasts to increase bone resorption by secreting parathyroid hormone-related peptide." (PMID 38397475, 2024). "Thus, blocking IL-6 during ICB therapy enhances tumor immunity and relieves irAE symptoms." (PMID 38760815, 2024). "Thus, IL-6 promotes tumor growth by facilitating immune evasion but is dispensable for cachexia." (PMID 38671295, 2024). "However, as the tumour progresses, the number of M2b cells increases and gradually replaces the M1 cell population and promotes tumour progression by secreting factors such as IL-10, IL-6 and IL-1." (PMID 39060648, 2024). "Moreover, IL-6 influences the tumor microenvironment by promoting angiogenesis, EMT, and altering the extracellular matrix, creating a hypoxic and nutrient-deprived environment that further contributes to genomic instability and the selection of aggressive cancer cell populations." (PMID 38689325, 2024). "Additionally, mRNA levels of interleukin-6 and tumor necrosis factor-alpha and active forms of signal transducer and activator of transcription 3 and nuclear factor-kappa B p65 were significantly increased in the tumor tissues of VDUP1 KO mice." (PMID 39272794, 2024). "Low serum levels of PGE2 (<6.5) and IL-6 (<45.8) were significant predictors of longer survival in dogs with anti-PD-L1 therapy (p = 0.033 and 0.031, respectively), whereas IL-2 and IL-6 predicted tumour response to c4G12 treatment (p = 0.030 and 0.013, respectively)." (PMID 38893123, 2024). "In a model of colorectal cancer, β1 integrin-rich EVs are secreted into circulation by tumor cells to activate resident fibroblasts in remote organs, which in turn induces a pre-metastatic niche and promotes metastatic cancer growth through the secretion of pro-inflammatory cytokines IL-6 and IL-8." (PMID 38254117, 2024). "Moreover, various cytokines such as IL-1β and IL-6, known to promote tumor development and progression, are found in the tumor ECM, along with the immune activator TNF-α, which is linked to anti-tumor immune response." (PMID 38955827, 2024). "Furthermore, particular importance is given to the function of FOSL1 in coordinating the activation of several cytokines, such as TGF-beta, and the commencement of IL-6 and VEGF production in tumor-associated macrophages (TAMs) that migrate into the tumor microenvironment." (PMID 38791400, 2024). "Furthermore, an analysis utilizing the TSIDB database uncovered a significant correlation between AEG-1 and several key factors, including the tumor-promoting cell Th2, immune activator IL6, CXCR4, immunosuppressants CTLA4, IL1, IDO1, LAG3, PDCD1, TGFB1, and the DHC molecule HLA-DPA1." (PMID 39483471, 2024). "In addition to its involvement in promoting cell migration and angiogenesis, IL-6 may hinder dendritic cell maturation, potentially suppressing immune activation specific to the virus or tumor." (PMID 38534385, 2024). "Therefore, CRP may also contribute to tumor progression by inducing the production of IL‐6 by macrophages, followed by STAT3 activation in tumor tissues." (PMID 39564003, 2024). "Furthermore, we sought to analyze the effect of TOP2A inhibition on IL-6 protein expression, which is one of the key cytokines in the tumor microenvironment confer resistance to chemo and radiotherapy and its overexpression has been reported in almost all types of tumors." (PMID 38957610, 2024). "Mesenchymal cells, including tumor-associated macrophages (TAMs) and cancer-associated fibrocytes (CAFs), interact with tumor cells by secreting cytokines and molecules, such as TGF-β and IL-6, to promote tumor growth, invasion, and metastasis and inhibit the activity of immune cells." (PMID 39194667, 2024).
tumor (continued). "Moreover, LPS-induced activation of TLR4 promotes inflammation by stimulating the production and release of pro-inflammatory cytokines (such as TNF-α, IL-1β, and IL-6), thereby indirectly contributing to neoplasia through maintaining proinflammatory microenvironment." (PMID 39328278, 2024). "Notably, IL6 hepatic secretion is differently regulated in men and women due to estrogens, which are able to counteract IL6 secretion by Kupffer cells in the liver and decrease tumour growth." (PMID 38396870, 2024). "Additionally, studies suggest that high expressions of CYFRA 21-1 and IL-6 in tumor tissue, IL-17 surrounding tumor cells, and the genes SDHAF2, MRPS34, MRPL11, and COX8A in cancer stem cells are associated with a poor prognosis, thus offering novel prognostic avenues for exploration." (PMID 39170710, 2024). "Alternatively, the blockade of tumor-derived factors such as IL-6, G-MCS and GM-CSF, involved in the differentiation process from GMPs/MLPGs but also in the acquisition of suppressive features, could represent a plausible approach to limit CD15+ monocyte accumulation." (PMID 39126041, 2024). "Thus, we conducted an analysis to assess whether serum IL-6 and/or IL-8, in combination with tumor markers, could predict clinical benefits with high accuracy." (PMID 38774604, 2024). "Elevated IL-6 levels in patients with mCRPC predict malignant prostate cancer progression and poor outcomes in patients with localized tumors Furthermore, we demonstrated that JunD inhibition results in GADD45α- and γ-dependent induction of cell death and inhibition of tumor growth." (PMID 38674385, 2024). "In addition, whether IL-6 inhibition may have differential tumor impacts depending on the timing of initiation, frequency of administration, or tumor type also remains an unanswered question." (PMID 39737191, 2024). "Therefore, the crosstalk between MET amplification and TNFA, as well as IFN-γ and IL-6 pathways, may have fostered the recruitment of neutrophil in the tumour." (PMID 39421445, 2024). "Therefore, MAOA-mediated modulation of ROS/IL-6 interactions may create a harmful cycle that promotes the transformation of naïve stroma into a phenotype that supports tumor growth." (PMID 39092186, 2024). "In addition, CD34, EDIL3, and TPM3 were positively correlated with signaling pathways related to tumor immune response, invasion, and metastasis, particularly the IL6/JAK/STAT3, inflammatory response, TNF-α signaling via NF-kB, and epithelial-mesenchymal transition." (PMID 38840234, 2024). "Notably, IL-6 has been found to be overexpressed in common metastatic organs such as lung, liver, brain, and bone marrow, which is conductive to the seeding of circulating tumor cells to establish metastatic lesions." (PMID 38520006, 2024). "In addition, IL-6 is produced by a variety of cells, such as T cells, B cells, monocytes-macrophages, fibroblasts, epidermal keratinocytes, endothelial cells, mesangial cells, and tumor cells, including cardiac myxoma cells in the human body." (PMID 38396907, 2024). "In addition, we found that among others IL-6 and IL-10 levels correlated with IL-8 levels, which may reflect the inflammatory microenvironment of the tumor, the latter also known for its inhibitory effect on the immunosurveillance." (PMID 39503874, 2024). "IL-6 released from the tumor may be a direct inducer of lipolysis and thermogenesis in adipocytes." (PMID 38474057, 2024). "In addition, sympathetic nervous system activation can indirectly lead to the release of several protumour factors, including matrix metalloproteinase-9 (MMP-9), VEGF, TGF-β, IL-6 and IL-8, triggering a series of inflammatory responses to stimulate tumour recurrence and metastasis." (PMID 38912060, 2024).
tumor (continued). "The decreases in IL-6 levels might be related to the effective control of tumor destruction in liver tissue by radiotherapy combined with immunotargeted therapy and reductions in tumor-mediated inflammation." (PMID 38769368, 2024). "Additionally, the tumour EGCs can also present a unique reactive phenotype, with increased expression of genes correlated with astrogliosis (e.g. Lcn2 and Timp1) and immunomodulatory functions (e.g. Ccl2 and Il6)." (PMID 38957473, 2024). "NETs may facilitate tumor cell migration and invasion by releasing pro-inflammatory cytokines and chemokines that attract tumor cells to the site of NETs deposition, including IL-1, IL-6, IL-8, and so on, promoting their movement toward distant sites." (PMID 39582869, 2024). "Therefore, heterogeneity among tumor cells influences the response to IL-6 stimulation." (PMID 39596207, 2024). "It has extensively been reported that these anti-tumour drugs impact the tumour microenvironment (TME), target human tumour-associated macrophages (hTAM), and inhibit the transcription of pro-inflammatory cytokines such as CCL2 (chemokine ligand 2), IL-6, VEGF, CCL3, CCL7, and CCL14." (PMID 38257245, 2024). "Elevated release of cytokines like interleukin-1, interleukin-6, and tumor necrosis factor α, disrupted hormone levels including growth hormones and estrogen, and alterations in the tumor microenvironment in HCC patients may all impair skeletal muscle function." (PMID 38321551, 2024). "However, N. sicca can also suppress tumor inflammation by downregulating NF-kB and IL-6." (PMID 39452698, 2024). "Since STAT3 phosphorylation (p-STAT3) can occur in response to cytokine IL-6 secreted by macrophages during DEN-induced tumor initiation and thus reflect liver inflammation, we investigated whether p-STAT3 levels were altered in Dnajb4–/– mice post-DEN injection." (PMID 39738726, 2024). "IL-6 may play a role in determining the degree of tumor invasiveness." (PMID 38716256, 2024). "Furthermore, GMI’s tumor-suppressive action was achieved by controlling the IL-6/Stat3 pathway." (PMID 39272862, 2024). "Additionally, in vivo experiments demonstrated that treatment with an IL-6 antibody decreases PD-L1 expression in tumor regions by modulating its glycosylation while enhancing JAK1/nonglycosylated PD-L1 association, JAK1-driven Tyr phosphorylation, and STAT3 recruitment." (PMID 39690423, 2024). "This demonstrates that IL-6 is a causal factor in cancer cachexia, regardless of tumor growth." (PMID 38510850, 2024). "CIK cells can kill tumor cells through multiple mechanisms, including the release of perforin and granzyme to directly lyse tumor cells, direct inhibition of tumor cells, or indirect regulation of immune function by secreting cytokines such as IL-2, IL-6, IFN-γ, and GM-CSF." (PMID 39221244, 2024). "However, the protein expression of the IL-6 pathway in tumor tissue has been scarcely addressed." (PMID 38881895, 2024). "However, IL-6 may also support T cell activation, proliferation and survival and boost cytotoxic function and anti-tumor activities." (PMID 39512342, 2024). "Therefore, in this study we aim to comprehensively assess the diagnostic value of individual and combined detection of serum IL-6 with traditional tumor markers, such as carcinoembryonic antigen (CEA) and cytokeratin 19 fragment (CYFRA21-1), in AIS patients in a large cohort of 300 cases." (PMID 38529301, 2024). "Using IL-6 blockade could reverse anti-PD-L1 resistance in HCC tumor model." (PMID 39075612, 2024). "Furthermore, STAT3's profound impact on the cellular inflammatory environment, highlighted by increased IL6 levels, may directly foster alterations in the tumor microenvironment, thereby affecting the phosphorylation and functional dynamics of LHPP." (PMID 39468431, 2024).